KRAS (KRas proto-oncogene, GTPase)
Diseases named in the same sentence as KRAS in open-access papers (continued):
Sharing a sentence is not in itself a finding about the gene and the disease.
tumor (continued). "High waist- and hip measures were associated with an increased risk of KRAS wild type tumours (ptrend = 0.045 and ptrend = 0.043), KRAS-mutated tumours (ptrend = 0.007 and ptrend = <0.001), as well as BRAF wild type tumours (ptrend = <0.001 and ptrend = <0.001)." (PMID 24918610, 2014). "A total number of 314 (63.7%) tumours were KRAS wild type and 180 (36.4%) were KRAS-mutated." (PMID 24918610, 2014). "We also examined survival separately for patients with KRAS wild-type tumors, KRAS mutated tumors, and missing or insufficient tumor tissue to assess whether survival differed between the testing periods for any sub-group." (PMID 24788807, 2014). "Therefore, there would be a greater likelihood of detecting KRAS mutations in patients with a larger tumor burden or after multiple lines of therapy." (PMID 25491325, 2014). "The interaction of primary tumor location and KRAS mutations suggests that primary tumor location might be an additional biomarker for EGFR-mABs." (PMID 24816724, 2014). "Mutations in RAS proto-oncogenes (comprising H-, N- and K-RAS) are among the most common in malignant tumours and although RAS isoforms are very similar, KRAS is more frequently found mutated in cancers occurring in 22% of all tumours analysed compared to 8% for NRAS and 3% for HRAS." (PMID 24720724, 2014). "Comparison of the clinicopathological features of the mutated KRAS, PIK3CA, NRAS genes with an all-wild type of these genes showed that the frequency of the intestinal type was significantly higher in patients whose tumor tissue contained KRAS mutations (P = 0.014)." (PMID 24774510, 2014). "In order to ascertain whether plasma KRAS analysis is predictive of tumor KRAS mutation status, we assessed DNA samples from both tumor tissue and pre-surgery plasma of 242 patients." (PMID 25491325, 2014). "One study conducted showed that KRAS mutation does occur in benign and malignant tumors, which can suggest that the mutation might be an early event in the pathogenesis of tumor progression." (PMID 24891964, 2014). "Of note, a significant interaction was only found between sex and BMI with respect to risk of KRAS-mutated tumours, and heterogeneity analysis was only significant for the highest tertile of WHR in relation to risk of KRAS-mutated compared to KRAS wild type tumours among women." (PMID 24918610, 2014). "Activating KRAS mutations represents the most common abnormality of a dominant oncogene in human carcinoma, with specificity and type of mutation varying in relation to tumor type." (PMID 24782938, 2014). "We examined KRAS mutations in codons 12, 13, 61 and 146 (assessed by pyrosequencing), in relation to clinicopathological features, and tumor molecular markers, including BRAF and PIK3CA mutations, CpG island methylator phenotype (CIMP), LINE-1 methylation, and microsatellite instability (MSI)." (PMID 24885062, 2014). "Although the mutation status of EGFR or other key genes in these patient tumor-derived cells is unknown, the status of KRAS, PIK3CA, or PTEN was mostly wild type." (PMID 25466244, 2014). "However, as therapy continues, more and more KRAS wild-type tumor are wiped out, the abundance of KRAS mutation becomes higher and patients tend to have a progression disease and become resistant to EGFR antibody therapy." (PMID 23874486, 2013). "Specifically, patients with codon 13 mutations reached a median survival of 28 months (95% CI 16–39), those with other rarer KRAS mutations a median survival of 33 months (95% CI 16–42) and patients with KRAS wild-type tumours a median survival of 29 months (95% CI 25–35)." (PMID 23374602, 2013). "In addition, the association of RBM5 and KRAS expression with clinicopathological parameters and tumor recurrence was analyzed." (PMID 23425895, 2013).
tumor (continued). "In the entire cohort, a similar survival was seen for patients with KRAS wild-type and codon 12-mutated tumours, while patients with tumours harbouring a KRAS codon 13 mutation had a significantly reduced CSS (HR = 1.94; 95% CI = 1.18–3.19) in unadjusted, but not in adjusted analysis." (PMID 24020794, 2013). "The malignant potential of tumour cells may be influenced by the molecular nature of KRAS mutations being codon 13 mutations less aggressive than codon 12 ones." (PMID 23506169, 2013). "Patients with KRAS mutated tumours had a significantly improved survival in unadjusted analysis, and this beneficial impact of KRAS mutations on survival was only evident in patients having well and moderately differentiated tumours, and patients being diagnosed in a less advanced clinical stage." (PMID 23800114, 2013). "Indeed, synergistic anti-tumor effects have been observed when PI3K/AKT and MEK pathways are both inhibited in preclinical tumor models, including a KRAS mutated lung cancer model." (PMID 24130864, 2013). "Furthermore, numerous studies have shown discordance in the KRAS mutational status between the primary tumor and the metastatic lesions." (PMID 24179521, 2013). "Why did tumor with low abundance of KRAS mutation tend to response to EGFR antibody therapy?" (PMID 23874486, 2013). "In this study, we first modified this PNA-PCR method to make sure that it could totally suppress amplification of KRAS wild-type DNA and confirmed its suppression ability on 47 tumor samples bearing KRAS mutations." (PMID 23874486, 2013). "A total number of 334 (63.7%) tumours were KRAS wild-type and 191 (36.4%) were KRAS-mutated." (PMID 24020794, 2013). "Second, we used unfixed tumor cells on touch imprints from the fresh cut tumor surface, and demonstrated that a validated KRAS mutation status could be obtained on the day of sample arrival." (PMID 24280411, 2013). "Indeed in preclinical experiments, transforming potential, RAS/GTP activation, MAPK phosphorylation and tumour growth were markedly increased in the presence of KRAS codon 12 mutations, followed in decreasing order by codon 13, 61, 117 and 146 mutations." (PMID 23374602, 2013). "Patient 9's tumor had notable mutations in KRAS (G12R) and PIK3CA (R93W)." (PMID 24204627, 2013). "Moreover, a total of 31 tumours were successfully analyzed for the presence of mutations in the gene encoding KRAS." (PMID 23408974, 2013). "The present study investigated the presence of KRAS mutations (mutated or wild-type) and their association with clinical-epidemiological and histopathological tumor features as well as the clinical outcomes of patients with metastatic colorectal adenocarcinoma." (PMID 29147353, 2013). "The mutational state of KRAS was determined and tumour was KRAS wild-type." (PMID 23426888, 2013). "Rare EGFR and KRAS mutations and tumor response to EGFR TKI." (PMID 23922984, 2013). "Since every screening method had its detection sensitivity, when the tumor KRAS mutation’s proportion reduced to a certain extent, this tumor sample might be recognized as KRAS wild type." (PMID 23874486, 2013). "The present study proved that PNA-PCR method could quantify and calculate the KRAS mutation’s abundance of tumor cells." (PMID 23874486, 2013). "Thus, km23-1 is required for another critical factor associated with the propensity of CRC cells to migrate and invade during tumor progression, despite the type of KRAS mutation that the cells contain." (PMID 23755307, 2013). "However, it does remain that CRC patients whose tumours harbour KRAS mutations have a high unmet medical need." (PMID 23356214, 2013). "Similarly, the wild-type and mutant KRAS signals were evenly distributed across the tumor areas with a higher expression of mutant compared to wild-type KRAS alleles." (PMID 24280411, 2013). "Correlation between percentage of KRAS mutation in tumor cells and disease control rate." (PMID 23874486, 2013).
tumor (continued). "Recent reports have suggested that the tumor suppressor activity of miRNA lethal 7a (let-7a) may be due to its association with KRAS and that inhibition of tumor growth may occur by suppression of K-Ras expression by let-7a." (PMID 23936455, 2013). "For patient 9's tumor, the KRAS (G12R) mutation was validated using a CLIA-certified test." (PMID 24204627, 2013). "There was a significant association between KRAS wild-type tumours and MSI." (PMID 24020794, 2013). "We tend to believe that this “secondary” KRAS mutation actually exists in primary tumor tissues." (PMID 23874486, 2013). "In summary, our study demonstrated that PNA-PCR method could easily detect the percentage of KRAS mutation in tumor cells." (PMID 23874486, 2013). "In our series this was the case for AREG, however tumour EREG mRNA retained predictive significance for survival both in KRAS wild-type as well as mutated cases, a counter-intuitive finding, further supported by the predictive significance of EREG for response, even in KRAS mutant patients." (PMID 23374602, 2013). "Quite possibly, KRAS mutations confer a tumor cell survival advantage following resection." (PMID 24194913, 2013). "Somatic mutations of PIK3CA may coexist with either KRAS or BRAF mutations within the same tumor, but KRAS and BRAF mutations appear to be mutually exclusive." (PMID 22931052, 2012). "However, one patient with a mutated KRAS tumor (1.2%) had a response in the CO.17 trial comparing cetuximab monotherapy with best supportive care (BSC) in patients with chemotherapy-refractory metastatic CRC." (PMID 22043994, 2012). "We detected KRAS mutations in 31.0% of the tumour tissue samples in our cases." (PMID 23226727, 2012). "Elevated expression of miR-200b, decreased miR-143 level and copy number losses may identify patients with mutated KRAS tumours who benefit from anti-EGFR therapy, whereas copy number gains in wild-type KRAS patients could predict resistance to cetuximab." (PMID 22804917, 2012). "Moreover, our study is the first to demonstrate an association between high AURKA-CN and improved clinical outcome among patients with mCRC receiving chemotherapy, with a more pronounced association noted among patients with KRAS wild-type tumours." (PMID 22240781, 2012). "Copy number gains in two wild-type KRAS tumours were associated with a poor PFS." (PMID 22804917, 2012). "To test whether the responsiveness of the 5 dpf epithelium to menadione was modified in a tumor model, we generated transgenic larvae that express an activated human KRAS allele in the intestinal epithelium (Tg(miR194:eGFP-KRASG12V))." (PMID 22973180, 2012). "To establish whether acquisition of the oncogenic kRas mutation in tumor cells alters their interaction with macrophages, we performed experiments in HCT116 and Hke-3 cells, isogenic cell lines that differ only by the presence of the mutant kRas allele." (PMID 23029025, 2012). "We compared KRAS point mutations between tumour tissue and blood samples." (PMID 23226727, 2012). "Mutations of PIK3CA, may coexist with either KRAS or BRAF within the same tumor, but KRAS and BRAF mutations appear to be mutually exclusive." (PMID 22586484, 2012). "The question of whether tumor KRAS/BRAF mutation status may be a reliable biomarker for the purpose of selecting high-risk patients to anti-EGFR therapy, however, remains elusive." (PMID 23226389, 2012). "Whether metastatic CRC patients carry the same KRAS mutation as the primary tumour is controversial." (PMID 23226727, 2012). "We also tested expression of each protein against all other clinicopathological variables (age, gender, Dukes stage, post-operative chemotherapy, pre-operative radiotherapy, site of tumour, KRAS mutation status, BRAF mutation status, MSI and trial group, i.e. placebo/rofecoxib)." (PMID 23154512, 2012).
tumor (continued). "Despite the limitations in sample size and concomitant treatment our results indicate that patients with KRAS copy number loss might benefit from treatment with an anti-EGFR antibody although their tumour is KRAS mutated." (PMID 22804917, 2012). "Five patients showed KRAS point mutations only in their primary tumour tissue samples." (PMID 23226727, 2012). "Overall, KRAS tumour mutation rate was 30% (145/478 positive cases)." (PMID 22931052, 2012). "Importantly though these findings highlight the necessity of carefully considering study design when analyzing markers that predict aggressive tumor biology, such as the KRAS-variant." (PMID 22662244, 2012). "We compared KRAS point mutations in tumour tissues and peripheral blood samples." (PMID 23226727, 2012). "Whether tumor KRAS mutation status is predictive for cetuximab-based CRT in LARC, is presently under debate." (PMID 23226389, 2012). "It is still debatable whether the assessment of KRAS mutations in the available primary tumour accurately indicates KRAS mutations in the corresponding metastasis." (PMID 23226727, 2012). "While the presence of a KRAS mutation permits identification of tumors that are insensitive to these treatments, only less than half of patients with a KRAS wild type (wt) tumor will benefit from treatments, suggesting a role for additional mechanisms of resistance." (PMID 22117530, 2011). "Briefly, SMAD4 deletion enhanced PAC pathogenesis directed by KRAS mutation, but also altered the tumor phenotype: tumors with SMAD4 deficiency were well-to-moderately differentiated and expressed epithelial markers, whereas tumors with intact SMAD4 frequently exhibited markers of EMT." (PMID 24212636, 2011). "Currently, we can speculate that when Cten expression is elevated in a tumour with KRAS/BRAF mutation, the association is likely to be causal." (PMID 21698197, 2011). "It has been proposed that the acquisition of a KRAS or BRAF mutation in a benign tumour might initiate the progression to an LMP tumour." (PMID 22163003, 2011). "KRAS G12D mutations have been shown to initiate carcinogenesis and tumour survival." (PMID 21781349, 2011). "The implication of these results for general oncology practice is that both tissue of primary tumour or liver metastasis may be used for KRAS mutation testing." (PMID 21364579, 2011). "Since KRAS is mutated in many cancers, we investigated whether this relationship could be demonstrated in other tumour models." (PMID 21698197, 2011). "In general, reported rates of KRAS mutation are somewhat lower in these sites than intra-hepatic cancers (3-20%) with a notable exception being neoplasms that arise in the setting of an anomalous union of the pancreatic and biliary ducts, which have higher rates of KRAS mutation." (PMID 21303542, 2011). "In five patients, the primary tumours had different KRAS mutations compared with the metastases." (PMID 21364579, 2011). "Genomic profiles were available for 8 KRAS mutant tumours, 31 wt and 16 tumours with unknown KRAS mutation status (untested SCC samples)." (PMID 21385341, 2011). "However, the difference in KRAS status was not clinically relevant in 5 of the 11 patients with discordant results, because both primary tumour and metastasis had a different KRAS mutation." (PMID 21364579, 2011). "However, as would be expected, tumours containing KRAS/BRAF mutation are refractory to the therapeutic effects of anti-EGFR antibodies." (PMID 21698197, 2011). "KRAS mutations analysis was successful in 130 of 132 tumours (98.4%)." (PMID 21949883, 2011).
tumor (continued). "KRAS mutation was detected in 108 out of 305 primary tumours (35.4%)." (PMID 21364579, 2011). "As Ras activation is likely to promote tumor cell proliferation to assess whether successful inhibition of the EGFR signaling pathway is associated with KRAS mutations cell lines were examined for KRAS gene mutations." (PMID 20565817, 2010). "Therefore, DNA was extracted from a KRAS-mutated patient tissue carefully reviewed to contain 40% tumor cells, and serially diluted with wt patient DNA." (PMID 21122130, 2010). "The KRAS mutation was associated with proximal location of the tumour." (PMID 20959826, 2010). "Again intriguingly, the highly amplified region includes the tumor-associated gene KRAS." (PMID 20398377, 2010). "Indeed, the knowledge of KRAS mutational status of a primary tumour is now mandatory for the treatment of metastatic disease, as it is a predictor of resistance to monoclonal antibodies of the epidermal growth factor receptor (anti-EGFR moAbs)." (PMID 20485284, 2010). "Of the 37 patients evaluable for tumour KRAS mutation status, 81% had KRAS wild-type tumours." (PMID 20959822, 2010). "In addition to those we also found two new novel mutations in KRAS oncogene in new procured tumor tissue samples." (PMID 20565773, 2010). "It has been known that KRAS point mutations are extremely infrequent in sporadic MSI-H tumours." (PMID 20959826, 2010). "A KRAS mutation was found in only 1 of 32 (3%) tumour samples analysed." (PMID 20068568, 2010). "KRAS mutational analysis is commercially available as a laboratory-developed test on tumor tissue." (PMID 20877448, 2010). "Five patients had KRAS mutations in the metastases (four with liver metastases and one with lung metastases) and wild type KRAS in the primary tumor, whereas the two other patients had KRAS mutations only in the primary tumor (1 with liver metastases and 1 with lung metastases)." (PMID 20020061, 2009). "KRAS mutations were detected in 3 (9.4%) of the tumours analysed." (PMID 19773760, 2009). "However, the presence of KRAS mutations appears to be associated with a lower chance of tumour response." (PMID 19229369, 2009). "KRAS functions in the receptor tyrosine kinase pathway and several other genes that function in this pathway are mutated in multiple tumour types." (PMID 19240718, 2009). "Moreover, when we stratified our results based on the primary tumor site, only tumors of colonic origin had a significantly higher frequency of KRAS mutations in primary tumors of patients with lung metastases." (PMID 20020061, 2009). "In the subgroup of 68 patients with KRAS 61 and 146 wild-type tumours, BRAF was mutated in 8 cases." (PMID 19603018, 2009). "We hypothesized that we missed some KRAS mutations by direct sequencing of tumour DNA, since malignant tumours are genetically heterogeneous." (PMID 17375050, 2007). "One PIK3CA mutation was found in a tumor that also contained a KRAS mutation." (PMID 17487277, 2007). "KRAS mutation is also a predictive and prognostic marker in other tumour types." (PMID 17184525, 2006). "Indeed, there is a universal presence of KRAS G12C mutations across tumor cells." (PMID 41541668, 2026). "The presence of a KRAS G12D mutation may further exacerbate tumour progression and bleeding." (PMID 41503246, 2026). "Similarly, KRAS p.Gly12Cys mutations were more frequent in Grade 3 tumors (15.2%) versus 7.6% in lower-grade tumors, in line with its known association with aggressive tumor behavior." (PMID 40725263, 2025). "Moreover, KRAS mutations have been shown to alter amino acids, fatty acids, and nucleotide biosynthesis in cancer cells, further highlighting the role of oncogenic mutations in promoting drug resistance across various tumor types." (PMID 40149342, 2025). "Furthermore, molecular studies have shown the presence of KRAS mutations and other molecular alterations in mucinous urachal neoplasms, which may aid in understanding tumor behavior and guiding future therapeutic interventions." (PMID 40062171, 2025).